BMP4 (bone morphogenetic protein 4)
Diseases named in the same sentence as BMP4 in open-access papers (continued):
Sharing a sentence is not in itself a finding about the gene and the disease.
Obesity (continued). "However, some researches demonstrated the BMP4 protein might be involved in obesity." (PMID 33910166, 2021). "We then utilized the PPI network to predict the mechanism of CHRDL1 in inducing obesity of PCOS patients, and the BMP4 signaling and IGF1 were identified." (PMID 33910166, 2021). "BMP2, BMP4, BMP6, BMP7, and BMP9 have been shown to affect the pathophysiological process of obesity and glucose metabolism beyond bone metabolism." (PMID 34258293, 2021). "Recently, it has been reported that BMP4 plays a key role to control metabolic homeostasis to mediate white adipose tissue (WAT) browning, and prevents obesity and insulin resistance in animal models." (PMID 32481541, 2020). "Early studies indicate that serum BMP4 is markedly increased in non-diabetic individuals with obesity and metabolic syndrome." (PMID 36457800, 2022). "Overall, BMPs, mainly including BMP9, BMP4, BMP2, and BMP7, may exert functions both in bone and in obesity as well as glucose metabolism." (PMID 34258293, 2021). "Besides, serum BMP4 was proven to decrease at 3 and 6 months after LSG in females with obesity along with decreased BMD." (PMID 34258293, 2021). "The results showed that BMP-4 levels were significantly higher in obesity with slight increased TSH than without increased TSH." (PMID 28376799, 2017). "Bone morphogenetic protein 4 (BMP4) is a proinflammatory and profibrotic factor, and the reduced expression of this molecule in obese mice seems to be inconsistent with the known proinflammatory effects of obesity." (PMID 25678859, 2015). "Because BMP-4 uses predominantly BMPR1A as its receptor, these results suggest that BMP-4/BMPR1A signaling may be involved in the pathogenesis of human obesity." (PMID 24170999, 2013). "Furthermore, increasing serum BMP4 levels in adult mice through gene therapy targeting the liver with AAV8 BMP4 promotes white adipose tissue browning, increases whole-body energy expenditure and prevents diet-induced obesity in initially lean mice." (PMID 33606810, 2021). "Moreover, considering the findings of this paper, the BMP4 inhibitor CHRDL1 is highly expressed in obesity but not in lean PCOS cases; the CHRDL1 gene may functions differently in normal or PCOS cases." (PMID 33910166, 2021). "For example, a signalling pathway involving BMP4 and its receptor BMPR1A influences insulin secretion and may contribute to obesity; mice lacking the HMGA2 homolog had a reduction in fat mass and were resistant to diet induced obesity." (PMID 24823714, 2014).
glioblastoma (38 papers, 2010 to 2025). The most malignant astrocytic tumor (WHO grade IV). "From a therapeutic perspective, this work pioneers the use of polyphosphazene-based nanoparticles for the delivery of BMP4-encoding plasmids in glioblastoma models." (PMID 40688657, 2025). "For example, BMP4 causes tumor-initiating cell depletion and inhibits tumorigenesis in glioblastomas; however, BMP4 induces EMT in pancreatic cancer cells." (PMID 26395571, 2015). "Previous studies suggest that BMP4 works through the directed differentiation of glioblastoma initiating cells [9,]." (PMID 40688657, 2025). "Chordin-like 1 (CHRDL1) has been identified as an “enforcer of stemness” in glioma stem cells, via antagonism of BMP4-induced glioblastoma differentiation and reduced tumorigenicity." (PMID 40277903, 2025). "Using these optimized nanoparticles, we delivered a BMP4-expressing plasmid (pBMP4) in glioblastoma models." (PMID 40688657, 2025). "Recently, researchers have reported that FSTL1 up-regulates the BMP4-Smad signaling in lung adenocarcinoma, while in glioblastoma, FSTL1 down-regulates the same signaling." (PMID 36756161, 2023). "Human recombinant bone morphogenetic protein 4 (hrBMP4) was used to treat 15 patients with glioblastoma recurrence after chemoradiation therapy." (PMID 38275375, 2023). "In the present study, we showed that, among the three DNA methyltransferases, the silencing of DNMT3A maintained the expression of PROM1 and the number of CD133‐positive glioblastoma cells, even in the presence of BMP‐4." (PMID 34214250, 2022). "To determine if PREX1-null glioblastoma cells had lost their multilineage potential, we treated them with BMP4." (PMID 34624316, 2021). "BMP4 plays a critical role during nervous system development andmaturation and it is found to be down regulated in glio-blastoma leading to poor outcomes,while treating glioblastoma cells with recombinant BMP4 has shown promising antitumoractions." (PMID 34612709, 2021). "For instance, the mesenchymal glioblastoma subtype expresses higher levels of BMP4 than proneural and classic GSC subtypes." (PMID 32102285, 2020). "Preliminary unpublished results from our laboratory showed increased phosphorylated SMAD1/5/9 and decreased multidrug resistance gene 1 (MDR1) expression, in pediatric glioblastoma KNS42 cells harboring an H3F3A G34V mutation, following BMP4 treatment." (PMID 32102285, 2020). "Here we show that activity of biologics (i.e., serum and Bmp4) that induces glioblastoma differentiation, as well as that of 57 epigenetic compounds, was significantly correlated across four different primary glioblastoma lines." (PMID 31637999, 2019). "To test the ability of MIEL to detect short term TPCs differentiation we treated four genetically distinct glioblastoma lines with serum or BMP4, then conducted MIEL analysis using either H3K9me3 and H3K4me1 or H3K27ac and H3K27me3." (PMID 31637999, 2019). "Our findings support the conclusion that p21 mediates the effect of BMP4 as an inhibitor of cell proliferation and a mediator of temozolomide resistance in glioblastoma." (PMID 31602000, 2019). "Previous studies have shown that BMP4 inhibited tumorigenesis in glioblastoma, myeloma and lung cancers." (PMID 30012194, 2018). "Administration of BMP4 to human glioblastoma-bearing mice induced CD133+ GSC differentiation and markedly attenuated CD133+ GSC sphere-forming frequency." (PMID 26880988, 2016). "This study provides new insights into BMP4’s dual roles in differentiation and senescence induction, underscoring the importance of understanding these mechanisms in a context-dependent manner when evaluating BMP4 as a therapeutic option for glioblastoma." (PMID 40362216, 2025).
glioblastoma (continued). "Polymeric materials were screened for non‐viral engineering of MSCs from multiple human donors to deliver bone morphogenic protein‐4 (BMP4), a protein previously investigated in clinical trials for glioblastoma (GBM) to combat a subpopulation of highly invasive and tumorigenic clones." (PMID 39545093, 2024). "The transcriptomic analysis suggests that BMP4 may increase glioblastoma tumor-initiating cells sensitivities." (PMID 36316503, 2022). "It is reported that BMP4 can inhibit the glioblastoma cell growth." (PMID 32508533, 2020). "Indeed, we observed distinct expression changes, including differences in expression of genes regulating chromatin organization and histone modifications, between serum- and Bmp4-induced glioblastoma differentiation." (PMID 31637999, 2019). "In addition, implantation of BMP4-treated glioblastoma xenografts to murine recipients resulted in smaller tumor lesions and substantially prolonged host survival compared with untreated controls." (PMID 26880988, 2016). "Indeed, an integrative study of mRNA and protein levels at single-cell resolution evaluating the effect of BMP4 (a proposed therapeutic agent for glioblastoma) on early-passage glioblastoma cultures identified extensive heterogeneity in how subpopulations of cells respond to BMP4 treatment." (PMID 34471925, 2022). "Therefore, BMP4 was a better prognostic marker in anaplastic gliomas and glioblastomas." (PMID 23590708, 2013). "BMP2 and BMP4 have been identified as key inhibitors of CSC self-renewal and drivers of CSC differentiation, for example in glioblastoma (GBM) stem cells." (PMID 40277903, 2025). "In glioblastoma stem cells, DYRK1A mimics the effect of BMP4, a member of the TGF family of cytokines, reduces cellular SOX2 levels, and promotes the differentiation of glioblastoma stem cells." (PMID 39482615, 2024). "The FSTL1-BMP4-Smad signaling has been reported in lung adenocarcinoma and glioblastoma, but the role of FSTL1 in BMP4-Smad signaling remains controversial." (PMID 36756161, 2023). "Given the variable differentiation response of GSC to BMP4, we first assessed how MMK1 and HW1 cells, two genetically distinct glioblastoma stem cell lines from our Q-Cell panel, respond to differentiation cues." (PMID 33924599, 2021). "This is due to the fact that BMP4 and BMP7 have also been found for their invasion-promoting activities in glioblastoma cells." (PMID 34357080, 2021). "We analyzed serum and BMP4, two established biologicals known to induce glioblastoma differentiation in culture and established signatures of the differentiated glioblastoma cells based on the pattern of epigenetic marks that could be applied across several genetic backgrounds." (PMID 31637999, 2019). "BMP2 and BMP4, which bind to the same receptor BMPR1, were shown to induce differentiation of glioblastoma-initiating cells." (PMID 24052948, 2013). "Moreover, BMP4 has been shown to be a GIC antagonist; pretreatment in vitro of glioblastoma cells inhibits their tumor-initiating capacity after injection of the cytokine." (PMID 22512247, 2012). "BMP4 methylation was a significantly beneficial factor for the OS of ACC, glioblastoma (GBM), LGG, prostate cancer (PRAD), and UCEC." (PMID 41169612, 2025).
glioblastoma (continued). "However, considering the GBM intra-tumoral heterogeneity and BIRC3 regional expression, we then analyzed BIRC3 and BMP4 expression using the IVY Glioblastoma Atlas dataset that has RNA-Seq datasets from MRI-distinct GBM regions." (PMID 35008722, 2021).
colorectal cancer (33 papers, 2011 to 2025). A primary or metastatic malignant neoplasm that affects the colon or rectum. "Our scientific contribution lies in adding an epigenetic dimension to the existing understanding of the role of BMP4 polymorphisms and gene expression in relation to colorectal cancer." (PMID 37628872, 2023). "One example is the oncogene encoding the bone morphogenetic protein 4 (BMP4), a member of the transforming growth factor‐ß family that is universally upregulated in human colorectal cancer cells and tissues." (PMID 33502116, 2021). "Despite the noncoding risk variant, the C allele of rs4444235 showed significantly increased allele-specific expression of the BMP4 gene in the colorectal cancer cell line." (PMID 31849324, 2019). "We performed an updated meta-analysis, using a comprehensive strategy of a logistic regression and a model-free approach, to evaluate more precisely the role of the rs4444235 variant near the Bone morphogenetic protein-4 (BMP4) gene in susceptibility to colorectal cancer (CRC)." (PMID 24932582, 2014). "Interestingly, variants within BMP4 have previously been associated with Parkinson's disease and colorectal cancer in other GWASs suggesting pleiotropic actions of this gene." (PMID 23704328, 2013). "Firstly, BMP4 gene variants have been shown to predispose to colorectal cancer." (PMID 23590708, 2013). "In cancer biology, it suppresses liver tumor-initiating cell characteristics by targeting CD13327and it inhibits colorectal cancer cell growth through suppression of autocrine BMP-4 signaling." (PMID 40287480, 2025). "Liraglutide, a member of the GLP-1RAs family, has been demonstrated to downregulate bone morphogenetic protein 4 (BMP4) expression in colorectal cancer (CRC) cells." (PMID 40140925, 2025). "Further analyses showed that αSMA+ CAFs in colorectal cancer inhibited the proliferation of Lgr5+ CSCs and promoted the differentiation of CSCs through BMP4/TGFβ1 signaling pathway, exerting tumor suppressive effects and inhibiting the CRC progression." (PMID 37124519, 2023). "In our comprehensive study of miRNA-target gene expressions in colorectal cancer, we have previously identified the overexpression of the BMP4 gene in colorectal cancer tissue." (PMID 37628872, 2023). "Our comprehensive genome-wide analysis highlights BMP4 as the most promising candidate gene with a potential role in the development and progression of colorectal cancer." (PMID 37628872, 2023). "In the context of colorectal cancer, the inhibition of BMP4 has been shown to induce apoptosis in colorectal cancer cells by reducing mitogen-activated protein kinase (MAPK) activity in cell culture." (PMID 37628872, 2023). "This significant finding was derived through the utilization of various bioinformatics tools, emphasizing the potential role of BMP4 in colorectal cancer development and progression." (PMID 37628872, 2023). "We conducted an intensive analysis of gene alterations in CRC from the TCGA database using an easy-to-use, interactive web portal, ALCAN, and the correlation between BMP4 gene expression and colorectal cancer clinical features." (PMID 37370018, 2023). "Aberrant activation of the Wnt/β-catenin pathway enhances BMP4 signaling in colorectal cancer cells." (PMID 33982211, 2021). "Based on all three E–P pairing approaches, BMP4 is potentially regulated by multiple enhancers located within a ~ 300 kbp region upstream of BMP4 in LoVo colorectal cancer cells." (PMID 33502116, 2021). "Another study also showed that T3 signaling is essential for BMP4-induced colorectal cancer cell differentiation." (PMID 32850840, 2020).
colorectal cancer (continued). "GRAIL analysis revealed 19 regions with a significant score, including the strongest connections with TGF-β signalling pathway genes such as TGFB1, SMAD7 and BMP4, thus suggesting a pivotal role of this pathway in colorectal cancer development." (PMID 27145994, 2016). "However, another report suggests that αSMA+ CAFs promote the differentiation of colorectal cancer stem cells through the BMP4/TGFβ1 signaling pathway, thereby inhibiting Lgr5+ CSCs." (PMID 37124519, 2023). "The identified connections showed that there was a higher-than-expected degree of connectivity, with a significance of PGRAIL<0.05 being observed for TGFB1, SMAD7 and BMP4. rs2238126 in ETV6 presented a weaker than expected connection with other genes reported in previous GWAS of colorectal cancer." (PMID 27145994, 2016). "BMP4 is up-regulated in human colonic adenocarcinoma and human colorectal cancer." (PMID 26239324, 2015). "Therefore, BMP4 may represent a potential treatment target, and further studies are required to elucidate the therapeutic potential in colorectal cancer patients with T2DM." (PMID 37370018, 2023). "And DJ-1 could promote colorectal cancer metastasis by activating PLAGL2-Wnt-BMP4 axis." (PMID 36408174, 2022). "BMP4 treatment can increase PTEN levels, inhibit the PI3K/AKT pathway, antagonize the proliferative effects of WNT, and induce the differentiation of colorectal cancer stem cells." (PMID 38049682, 2023). "As expected, tumor-derived organoids highly expressed in vivo tumor-specific genes, many of which have been widely reported to be closely related to colorectal cancer progression and metastasis, such as PROCR, SCD, BMP4, CEACAM6, TESC, and TGFBI." (PMID 35484598, 2022). "Expression of BMP2, BMP4, BMP5, BMP6, BMP9 and osteocalcin has been reported in colorectal cancer with heterotopic ossification." (PMID 29029440, 2017). "Furthermore, BMP4, which we identified as a specific ligand in MC, is a member of the TGF-β superfamily and is related to colorectal cancer progression." (PMID 37091868, 2023). "In cancer, BMP4 was shown to promote CSC differentiation, leading to diminished tumorigenic capacity and increased sensitivity to chemotherapy drugs in hepatocellular carcinoma and colorectal cancer models." (PMID 33649296, 2021). "Among the five ligands that were found only in MC tissues, bone morphogenetic protein 4 (BMP4), hyaluronic acid synthase 2 (HAS2), and heparin-binding epidermal growth factor-like growth factor (HBEGF) were reported to be involved in cell proliferation or cell migration in colorectal cancer." (PMID 37091868, 2023). "Interestingly, elevated expression of BMP4 is specific to colorectal cancer, while other BMPs are not elevated in colorectal cancer cells." (PMID 38049682, 2023).